PIK3CA (phosphatidylinositol-4,5-bisphosphate 3-kinase catalytic subunit alpha)
Diseases named in the same sentence as PIK3CA in open-access papers (continued):
Sharing a sentence is not in itself a finding about the gene and the disease.
cancer (continued). "PIK3CA plays a pivotal role in cell metabolism and proliferation and whose alterations are commonly found in a variety of cancers." (PMID 34599863, 2021). "According to the Catalog of Somatic Mutations in Cancer (COSMIC), somatic mutations in the PIK3CA gene occur in about 26.4% of BCs in women." (PMID 34680380, 2021). "This study will provide new ideas and a basis for precision treatment of cancer patients with PIK3CA alterations." (PMID 34249689, 2021). "Ultimately, in the setting of PIK3CA wild type HNSCC the direct cancer-targeting and antitumor immune effects of CDX-3379 are augmented by concomitant anti-PD-1 blockade, leading to increased durable responses to the combination of anti-PD-1 and HER3i." (PMID 33888713, 2021). "This study focused on the contributions of PIK3CA mutants to higher-order genetic marginal effects on the hazard ratio (HR) and overall survival (OS) probability across three different cancer types." (PMID 33827485, 2021). "Frequently detected genetic alterations (>5% in >5 samples across all studies) in GBC for which targeted therapies are available in other cancer types included mutations in ATM, ERBB2, and PIK3CA, and ERBB2 amplifications." (PMID 34771420, 2021). "PIK3CA activating mutations are able to enhance mTOR activity and inhibit autophagy in HPV(+) HNSCC, leading to the predisposition of these cancer cells to avoid autophagy, ferritinophagy and ferroptosis." (PMID 34072836, 2021). "Cancer-related genes commonly amplified from 3q26 include PIK3CA, TBL1XR1, DCUN1D1, SOX2, MECOM, PRKCI, and TERC." (PMID 34436017, 2021). "Although activating variants of PIK3CA are frequent in some tumors of different tissue origin, at present, there is insufficient evidence to consider PROS with increased cancer risk." (PMID 34944785, 2021). "A mutated form of the PIK3CA protein was also found to selectively phosphorylate AKT and FOXO promoting cellular growth and cancer cell invasion." (PMID 34503172, 2021). "Upregulation of PIK3CA is frequently observed in CRC, and CRC patients with PIK3CA mutations have poor cancer-specific survival." (PMID 34571860, 2021).
cancer (continued). "Alternative means of activating the PI3K pathway in basal-like cancers probably include loss of PTEN and INPP4B and/or amplification of PIK3CA." (PMID 34888495, 2021). "In comparison with PIK3CA, mutations in PIK3R1 are less common but have been found in various cancers including endometrial, colorectal, breast and pancreatic." (PMID 32677674, 2020). "Hyperactivation of this pathway is commonly detected in many types of cancers, including MCC4,27,28,30,41, and oncogenic mutations in PIK3CA gene have been detected in 4–10% of MCC26,27." (PMID 32483262, 2020). "As a result, this pathway is activated in cancer cells through various mechanisms involving genomic alterations in the pathway components (e.g., PIK3CA, PIK3R1, PTEN, AKT, TSC1, TSC2, LKB1), some of which are therapeutic targets." (PMID 33322834, 2020). "Mutations in PIK3CA, resulting in upregulation of the PI3K/AKT/mTOR pathway, have been identified in many cancer types, including in BTC." (PMID 32722188, 2020). "Many PIK3CA mutant cancer cell lines have also been shown to exhibit transformed phenotypes despite displaying minimal AKT activation, suggesting AKT-independent mechanisms that must be considered." (PMID 32365913, 2020). "PI3K inhibitors are reported to not only induce the activation of the oncogene Myc but also stimulate the amplification of PIK3CA, both of which reduce cancer cell sensitivity." (PMID 32171304, 2020). "PIK3CA is a key down-stream protein kinase of the PI3K-AKT signaling pathway playing an important role in cancer cell proliferation, catabolism, cell adhesion and apoptosis." (PMID 32410843, 2020). "It is noteworthy that heterozygous PIK3CAH1047R on its own rarely suffices to induce cancer in mice, consistent with the benign disease in individuals with congenital PIK3CA-related overgrowth." (PMID 32010943, 2020). "While NGS analysis unveiled common mutations in PTEN, CTNNB1, and ARID1A, different PIK3CA and PIK3R1 mutations were also detected, suggesting the existence of at least two cancer clones." (PMID 32652986, 2020). "In summary, these data show that PIK3CA activation overrides regulation of stemness traits by IL-6 trans-signaling and renders cancer cells more independent from microenvironment control." (PMID 33020483, 2020). "The PI3 kinase complex, consisting of the catalytic component (PIK3CA) and the regulatory component (PIK3R1), has also been implicated in many cancers." (PMID 33237934, 2020). "PIK3CA-AKT-mTOR signaling pathway is frequently activated in human cancers, and many small-molecule inhibitors have been developed that target various nodes in the pathway." (PMID 32782388, 2020).
cancer (continued). "Raptor is also highly expressed in PIK3CA mutant cancer tissues compared to PIK3CA wild type (p < 0.05)." (PMID 32000660, 2020). "A2780 and OV2008 cancer cells, with loss of PTEN and PIK3CA E545K mutation, are highly malignant with strong migration and invasion abilities." (PMID 32860347, 2020). "A recent study has revealed that MYC alterations are mutually exclusive with PIK3CA, PTEN, APC, or BRAF alterations, suggesting MYC amplification as a distinct driver mutation in the cancer genome." (PMID 32235890, 2020). "As previous report, our data showed that MB sequencing also detected PIK3CA, ERBB2 and KRAS subclonal mutations, which are linked to therapy response in various cancers." (PMID 32099048, 2020). "Across all cancer types, MpBC showed the highest frequency of alterations in EGFR and PTEN, and a modest percentage of PIK3CA mutations." (PMID 33148288, 2020). "The preliminary results of the POSEIDON trial, testing tamoxifen plus Taselisib or placebo plus tamoxifen, support antitumor activity in both PIK3CA mutant and wild-type cancers." (PMID 32210163, 2020). "Amongst the most common mutations across all cancers that also occurred in GBCs were KRAS G12/G13 (5 samples), PIK3CA H1047/E545/E542 (6 samples) and NRAS Q61 (1 sample)." (PMID 32839463, 2020). "In cancer cells, YB-1 has been shown to activate the expression of several genes important for cell proliferation, such as DNA polymerase α, cyclins, PIK3CA, EGFR and HER-2, with some of these molecules being implicated in trophoblast proliferation." (PMID 32842598, 2020). "For example, PIK3CA H1047R and PLCG1 S273F are frequently identified as activating mutations in human cancers." (PMID 32210430, 2020). "There are numerous types of assays and methods used in clinical studies to determine PIK3CA status in cancers." (PMID 32697890, 2020). "Taselisib showed greater activity among the 152 patients who had PIK3CA mutant cancer cells detected at baseline, with 56.2% showing an ORR compared to 38% of patients who received placebo ([OR] 2.03, 95%CI 1.06–3.88, p = 0.033)." (PMID 32429381, 2020). "Data on genetic alterations in seromucinous carcinoma are limited, although one international study showed mutations in ARID1A, KRAS, PIK3CA, and PTEN in 16%, 70%, 37%, and 19% of seromucinous carcinoma, respectively, based on analysis of 32 cases." (PMID 32023964, 2020).
cancer (continued). "Studies have demonstrated that PIK3CA mutations and amplifications contribute to the hyperactivation of the PI3K/Akt pathways in breast and other human cancers." (PMID 30867034, 2019). "It is worthwhile mentioning that PIK3CA probably regulates some common molecules or pathways in different cancer." (PMID 31472672, 2019). "Several other studies reported the amplification of genomic regions containing AKT, PDPK1, or PIK3CA genes in various cancer types." (PMID 31905960, 2019). "This differential was duplicated in an examination of two separate studies of patients with LUSC, which showed 20–50% lower levels of PIK3CA gene expression among patients who were dead at 1, 3, and 5 years after cancer." (PMID 31221127, 2019). "Our analyses demonstrated that PIK3CA and PTEN mutations co-occurred significantly in pan-cancer cell lines (p = <0.001)." (PMID 31289610, 2019). "The PIK3CA gene, which encodes the p110α catalytic subunit of PI3 kinase (PI3K), is mutationally activated in cancer and in overgrowth disorders known as PIK3CA-related overgrowth spectrum (PROS)." (PMID 30948643, 2019). "Several other cancer driver genes, such as ARID1A, FAT4, and PIK3CA, were also found to mutated in more than 10% of GC samples." (PMID 31781598, 2019). "The involvement of the PIK3CA gene in a wide variety of common human cancers has been well supported by many studies." (PMID 31530827, 2019). "Molecular subtyping is a cornerstone of precision medicine in cancer treatment, and the mutation status of genes in the EGFR pathways, including RAS genes, PIK3CA, PTEN and BRAF have been shown to predict response to EGFR blockade therapy in CRC." (PMID 31775679, 2019). "Combined with the finding of multiple PIK3CA mutant copies in human cancers, this suggests that a signaling threshold determines the disease consequences of PIK3CAH1047R, one of the commonest human oncogenic mutations." (PMID 30948643, 2019). "Other genes which feature across multiple types of cancer and enter the top five driver-gene list are PIK3CA (in 6), KRAS (in 5) and CTC-297N7.11 (in 4)." (PMID 31530827, 2019). "Differential regulation of downstream genes in CMTs with the PIK3CA (H1047R) mutation, such as up-regulated PCK2 and down-regulated CDKN1B, allows cancer cells to utilize an alternative catabolic pathway." (PMID 31842489, 2019). "Amplification of the oncogenes ERBB2, CDK6, MDM2 affected dependency, as did point mutations in PIK3CA, KRAS, NRAS, VHL and BRAF, validating our approach to highlight genes with significance in cancer." (PMID 30803482, 2019). "Other novel, highly scoring gene pair predictions that included cancer associated genes included PARP1 with PBRM1, BRCA2, ARID1A and APC as well as PIK3CA with MAP2K1, ABL1 and EGFR." (PMID 30995217, 2019). "A lot of genes related to PIK3CA found in our research has been reported to correlate with other cancer types, which proved the importance of PIK3CA." (PMID 31472672, 2019). "Based on these findings, we aimed to identify proteins associated with this resistance to MEK inhibition in KRAS and PIK3CA mutant cancers." (PMID 30944457, 2019). "This identified 67 genes of which 50 have been previously reported to be show some association with cancer (including NOTCH1 and PIK3CA) using PUBMED search." (PMID 31427592, 2019).
cancer (continued). "The mutationd of three hotspots at the 542nd or 545th and the 1047th amino acids, in exon 9, and exon 20 of PIK3CA, respectively, are established in HBC and both mutations are known as gain-of-function mutations resulting in cancer transforming capacity." (PMID 31842489, 2019). "Previous studies commonly reported that mutations in oncogenes such as KRAS, PIK3CA, BRAF were associated with clinical outcomes in various cancers." (PMID 30871151, 2019). "PIK3CA, the gene encoding p110α, the catalytic subunit of phosphatidylinositol 3-kinase (PI3K), is one of the most frequently mutated genes in human cancer." (PMID 31652979, 2019). "A previous report suggests that HPV− HNSCC is characterized by a tobacco-associated mutational signature, while HPV+ cancers display an APOBEC3 signature and APOBEC3-mediated driver mutations, including characteristic helical domain PIK3CA mutations." (PMID 30647454, 2019). "Shortly after, the same group further showed that PIK3CA-mutant cancer cells sensitive to BYL719 tend to potently inhibit phosphorylation of retinoblastoma protein (RB), a substrate of CDK4/6, whereas resistant cells failed to do so." (PMID 35582276, 2019). "Oncogenic signals, including Myc, PIK3CA hotspot mutations (H1047R and E545K) and KRAS hotspot mutation (G12V), upregulate ATF4 to promote cancer survival." (PMID 31064130, 2019). "Mutations can inactivate or constitutively activate pathways, as demonstrated for frequent mutations in cancer, such as in BRAF and PIK3CA, that play casual roles in tumorigenesis." (PMID 30921324, 2019). "For example, PIK3CA is often perturbed by either SMs or CN amplifications although prevalence of each type is different in different cancer types." (PMID 31276486, 2019). "Gene amplifications of PIK3CA are also common in some cancer types and can contribute to an aggressive phenotype." (PMID 30650664, 2019). "The advent of novel targeted therapies against PI3K pathway has further increased the significance of the assessment of PIK3CA gene alterations in cancers." (PMID 29704890, 2019).